REN (renin)
Diseases named in the same sentence as REN in open-access papers (continued):
Sharing a sentence is not in itself a finding about the gene and the disease.
endothelial dysfunction (continued). "They both play major roles in the heme synthesis pathway, increased oxidative stress and inflammation, nitric oxide production, endothelial dysfunction, and regulation of the renin-angiotensin-aldosterone system, which may be how they jointly contribute to high BP." (PMID 39683541, 2024). "Furthermore, increased sympathetic activity may activate the renin-angiotensin-aldosterone system, further perpetuating endothelial dysfunction and systemic vascular resistance." (PMID 39161550, 2024). "Several shared mechanisms, including chronic inflammation, activation of the renin–angiotensin–aldosterone system (RAAS), and endothelial dysfunction, might explain the association between pre-existing uncontrolled BP, high IL-6, and IL-17 concentrations, and long COVID in patients undergoing HD." (PMID 38424126, 2024). "Thus, excessive oxidative stress due to varying SUA levels may lead to induced endothelial dysfunction, affect the extent of activation of the renin-angiotensin system and indirectly contribute to the increased risk of all-cause mortality." (PMID 36915709, 2023). "Accumulating evidences suggest that OSA might contribute to various renal diseases via its association with increased sympathetic nervous system activity, endothelial dysfunction, inflammation, renin-angiotensin-aldosterone system overactivation, and increased oxidative stress." (PMID 36874972, 2023). "Studies have demonstrated that IR may contribute to stroke onset and progression through multiple pathways: platelet activation; aggregation; endothelial dysfunction; smooth muscle cell dysfunction; or overactivation of the renin-angiotensin system, among others." (PMID 38093283, 2023). "It plays a central role in activation of the renin–angiotensin–aldosterone system, reduction of bioavailable nitric oxide, and remodeling of the vascular extracellular matrix, all of which contribute to endothelial dysfunction, vessel wall hypertrophy and fibrosis, and vascular elasticity reduction." (PMID 36440032, 2022). "In the present review we discuss the different mechanisms that may contribute to explain the pathophysiology of COVID-19 including viral entrance, direct viral toxicity, endothelial dysfunction, thromboinflammation, dysregulation of the immune response, and the renin–angiotensin–aldosterone system." (PMID 33648564, 2021). "Hyperinsulinemia/insulin resistance may induce sodium reabsorption by the distal nephron segments, resulting in increased release of angiotensin II, the main effector peptide of the renin-angiotensin system, and enhanced sympathetic activity, vascular resistance, and endothelial dysfunction." (PMID 34579668, 2021). "The increased weight or waist–hip circumference due to adiposity and consequent endothelial dysfunction due to renin–angiotensin–aldosterone dysregulation, poor shear stress and metabolic flexibility might be the putative mechanisms of the higher MAP in these young adults." (PMID 34682938, 2021). "On the other hand, many studies have shown that AF leads to endothelial dysfunction for many reasons, including increased shear stress, decreased nitric oxide bioavailability, increased oxidative stress, inflammation, and abnormalities of the renin-angiotensin system." (PMID 33443627, 2021). "In conclusion, this review presents different mechanisms that may contribute to explain the pathophysiology of COVID-19 including viral entrance, direct viral toxicity, endothelial dysfunction, thromboinflammation, dysregulation of the immune response, and the renin-angiotensin-aldosterone system." (PMID 33648564, 2021). "CRP was reported to be effective on endothelial dysfunction in a way that high levels may reduce nitric oxide production, increase endothelin 1, and up-regulate angiotensin type 1 receptor, therefore, influencing on renin-angiotensin-aldosterone system." (PMID 32489776, 2020).
endothelial dysfunction (continued). "Free fatty acid-mediated endothelial dysfunction involves several mechanisms including impaired insulin signaling and nitric oxide production, oxidative stress, inflammation and the activation of the renin-angiotensin system and apoptosis in the endothelial cells." (PMID 28750629, 2017). "There are many factors including sleep cycle and the renin-angiotensin-aldosterone system, intermittent hypoxia-induced endothelial dysfunction and artery stiffness, and renal tubular dysfunction-related nocturnal natriuresis that may impact kidney function from OSA." (PMID 27380033, 2017). "Therefore, blockade of the renin-angiotensin system with ACEIs/ARBs may improve endothelial dysfunction." (PMID 26809145, 2016). "Chronic intermittent hypoxia and sleep fragmentation may result in inflammation, oxidative stress and activation of the sympathetic nervous system and renin-angiotensin-aldosterone system, and, in turn, endothelial dysfunction and glomerular hypertension may increase urinary albumin excretion." (PMID 24265736, 2013). "Oxidative stress, endothelial dysfunction, and vascular inflammation could be therapeutic targets when the renin-angiotensin-aldosterone system is activated by accumulation of conventional cardiovascular risk factors; however, a strategy for management of CRS has not been established yet." (PMID 22792467, 2012). "Mechanistic links between vitamin D deficiency and AH in DKD are discussed, with emphasis on maladaptive activation of the renin-angiotensin-aldosterone system (RAAS), persistent inflammation, oxidative stress, endothelial dysfunction, and insulin resistance." (PMID 41827616, 2026). "As a result, its pathophysiological mechanisms have been studied extensively and are focused around pressure natriuresis, the renin–angiotensin system (RAS), the sympathetic nervous system, oxidative stress, and endothelial dysfunction." (PMID 39858537, 2025). "Endothelial dysfunction induced by cytokines (IL-1, IL-6, TNF-α) increases capillary permeability and interstitial oedema, while activation of the renin-angiotensin-aldosterone system and natriuretic peptides exacerbates venous congestion and organ damage." (PMID 40585555, 2025). "Different mechanisms are involved in the prothrombotic state of COVID-19 patients, including a dysregulated renin–angiotensin–aldosterone system (RAAS), endothelial dysfunction, elevated von Willebrand factor (vWF), and a dysregulated immune response." (PMID 40226433, 2025). "Microbial translocation, endothelial dysfunction, abnormal activation of the RAAS (renin–angiotensin–aldosterone system), renal disease, dyslipidemia, sympathetic activation, and immune reconstitution have been suggested as possible mechanisms." (PMID 41302171, 2025). "Recent studies have shown that non-dipper hypertension is characterized by elevated nighttime sympathetic activity and sustained renin-angiotensin-aldosterone system (RAAS) activation, leading to persistent endothelial dysfunction and vascular inflammation." (PMID 39768879, 2024). "Endothelial dysfunction arises from the intricate interplay of inflammatory pathways, including the TGF-β, NF-κB, and renin-angiotensin systems, which promote fibrosis and impair vascular function." (PMID 39125842, 2024). "Renin–angiotensin–aldosterone system (RAAS), the sympathetic nervous system (SNS), endothelial dysfunction, hyperinsulinemia, adipokine imbalance, and increased inflammatory cytokines, increase in intraabdominal pressure, glomerular and tubular effects." (PMID 37749166, 2023). "Proposed mechanisms linking HTA with liver disease include activation of the renin–angiotensin–aldosterone system (RAAS), insulin resistance, and endothelial dysfunction-related arterial stiffness." (PMID 36114231, 2022).
endothelial dysfunction (continued). "On the other hand, overweight/obesity might induce HTN and other CVD by activating the renin–angiotensin–aldosterone system, increasing sympathetic activity, promoting insulin resistance and leptin resistance, increased procoagulatory activity, and endothelial dysfunction." (PMID 36376985, 2022). "This could be attributed to a number of factors as obesity stimulates the activation of the renin-angiotensin-aldosterone system, an increase in sympathetic activity, which further promotes insulin and leptin resistance, and an increase in procoagulatory activity and endothelial dysfunction." (PMID 33898368, 2021). "Four major mechanisms are thought to be involved in COVID-19 pathogenesis, including the activation of the renin-angiotensin system (RAS) signaling pathway, oxidative stress and cell death, cytokine storm, and endothelial dysfunction." (PMID 34064039, 2021). "Multiple mechanisms are involved in determination of renal damage inhypertension, such as the renin-angiotensin-aldosterone system (RAAS), oxidativestress, endothelial dysfunction, and inflammation." (PMID 33475676, 2021). "COVID-19 patients exhibited very similar levels of endothelial dysfunction, coagulation/fibrinolysis, and inflammation parameters, compared to cirrhotic patients, as well as RAS activation, indicated by increased plasma renin concentration." (PMID 34945736, 2021). "We investigated the renin-angiotensin-aldosterone system (RAS), parameters of endothelial dysfunction, inflammation, and coagulation/fibrinolysis in cirrhotic patients and in COVID-19 patients." (PMID 34945736, 2021). "On the other hand, CS is initiated by a reduction in cardiac output and subsequently affected by an activation of the renin–angiotensin–aldosterone system (RAS) and endothelial dysfunction." (PMID 34640526, 2021). "The renin-angiotensin system (RAS), OS and cell death, cytokine storm, and endothelial dysfunction are four main pathways in COVID-19 pathogenesis." (PMID 33082858, 2020). "The proposed mechanism of increased LV wall thickness include insulin resistance, increased renin-angiotensin-aldosterone system (RAAS), and endothelial dysfunction and inflammation." (PMID 32345225, 2020). "High serum urate activates the renin-angiontensin system, promotes inflammation, accelerates LDL oxidation, reduces the nitric oxide, and induces endothelial dysfunction." (PMID 32295651, 2020). "Metabolic syndrome contributes to kidney disease through multiple interconnected mechanisms, including inflammation, oxidative stress, activation of the renin–angiotensin–aldosterone system (RAAS), increased sympathetic nervous system (SNS) activity, and endothelial dysfunction." (PMID 41597505, 2026). "Mechanistically, deficiency may contribute to myocardial remodelling through overactivation of the renin–angiotensin–aldosterone system (RAAS), oxidative stress, and endothelial dysfunction." (PMID 41437990, 2025). "As a result, activation of the sympathetic nervous system, the Renin–Angiotensin–Aldosterone (RAAS) axis, endothelial dysfunction, oxidative stress, and inflammation may contribute to the chronic deterioration of cardiac function." (PMID 40299538, 2025). "Although initially attributed to the renin-angiotensin-aldosterone system (RAAS), TGF-β1, OS, and matrix metalloproteinases (MMPs), emerging evidence suggests that endothelial dysfunction-marked by reduced NO bioavailability-serves as a pivotal mechanism in this process." (PMID 41282011, 2025). "The typical indicators of VILI are the release of inflammatory mediators, barrier disruption, activation of the renin–angiotensin-system (RAS) and other forms of endothelial dysfunction such as glycocalyx shedding and endothelial nitric oxide synthase uncoupling." (PMID 39859396, 2025). "The renin–angiotensin–aldosterone system (RAAS) activation, initially compensatory, leads to long-term adverse effects including fibrosis, oxidative stress, and endothelial dysfunction." (PMID 40703630, 2025).
endothelial dysfunction (continued). "The effect of smoking on postoperative AKI has not been fully investigated, but it is thought to involve endothelial dysfunction, activation of the renin-angiotensin system, and oxidative stress." (PMID 39607542, 2024). "We showed endothelial dysfunction in cultured CiGEnCs evidenced by enhanced transcription and translaton of ICAM-1, VCAM-1, vWF, and ET-1 in response to Ang II stimulation to simulate the activated renin-angiotensin system in patients with malignant HTN." (PMID 37188751, 2023). "Numerous studies revealed that not only FO, but also renin-angiotensin-aldosterone system (RAAS) system activation, endothelial dysfunction, and proinflammatory factors overexpression existed in CKD with moderate-to-serious renal dysfunction, which was related to LVH." (PMID 35284436, 2022). "It was proposed that intermittent hypoxemia, activation of the renin–andiotensin–aldosteron (RAA) system, endothelial dysfunction, sleep fragmentation and nocturnal fluid shift may play a role in increases in blood pressure." (PMID 32204495, 2020). "There was a weak risk factor-independent relationship between high renin levels and a lower RHI among T2D subjects, but otherwise we found no independent associations with arterial stiffness or endothelial dysfunction." (PMID 27596252, 2016). "Plasma levels of renin, angiotensin I (Ang I), angiotensin II (Ang II), angiotensin 1-7 (Ang 1-7), the Ang II/Ang I ratio (as a surrogate of ACE activity), and asymmetric dimethylarginine (ADMA)-a marker of endothelial dysfunction -were measured at baseline (D0) and day 3 (D3)." (PMID 41663785, 2026). "Given that standard pharmacologic management with renin-angiotensin-aldosterone inhibitors, while essential for reducing intraglomerular pressure and proteinuria, does not fully address persistent OS and endothelial dysfunction, there is a compelling rationale to explore complementary strategies." (PMID 40869029, 2025). "Fourth, there is a limitation to explaining the mechanism of an independent role of platelets in microvascular endothelial dysfunction due to a lack of data about thrombopoietin, C-reactive protein, pro-inflammatory cytokines, renin, angiotensin II, or aldosterone in this study." (PMID 38248790, 2024). "Vasopressin contributes to vasoconstriction by different mechanisms: stimulation of the renin–angiotensin–aldosteron system (RAAS), direct effect on smooth muscle cells, or via secretion of endothelin-1 (ET-1) from endothelial cells, which aggravates endothelial dysfunction." (PMID 31187425, 2019). "The local tissue renin-angiotensin-aldosterone system (RAAS) in the vascular tissue and immune cells and perivascular adipose tissue is recognized as an important element involved in endothelial dysfunction which contributes significantly to arterial stiffness." (PMID 24194732, 2013). "Thus, endothelial dysfunction with the impairment of NO-dependent vasodilatation can be induced by hyperinsulinemia, excessive ROS and RNS (reactive nitrogen species) production, and it could be amplified by hyperuricemia, inflammation, or activation of the renin–angiotensin system ‘RAS’." (PMID 31835800, 2019).
COVID-19 (437 papers, 2020 to 2026). A disease caused by infection with severe acute respiratory syndrome coronavirus 2. "The S-CoV group showed a reduced abundance of pathways involved in steroid hormone synthesis (including androstenedione degradation), a process regulated by ACTH and the renin-angiotensin-aldosterone system (RAAS) that is linked to COVID-19 severity." (PMID 40433668, 2025). "Obesity is a major risk factor for severe COVID-19, partly explained by chronic systemic low-grade inflammation and renin-angiotensin-aldosterone system (RAAS) dysregulation." (PMID 41562075, 2025). "In particular, ACE2 rs2074192 is associated with an increased incidence of diseases characterised by renin-angiotensin system dysregulation, including increased susceptibility to COVID-19 and increased disease severity." (PMID 39920116, 2025). "Renin–angiotensin–aldosterone system dysregulation is an important mechanism in several co-morbidities that increase the susceptibility to severe COVID-19, including hypertension and diabetes." (PMID 39518552, 2024). "Hypercytokinemia, the renin-angiotensin system, hypoxia, immune dysregulation, and vasculopathy with evidence of immune-related damage are implicated in brain morbidity in COVID-19 along with a wide variety of genomic and environmental influences." (PMID 38360666, 2024). "ANPEP and ACE are two genes that have been implicated in COVID-19 due to their involvement in the renin-angiotensin-aldosterone system (RAS)." (PMID 38813031, 2023). "The spike protein bound to the membrane protein, ACE2, represents the essential condition for transmission and begins the association between COVID-19 and the renin-angiotensin–aldosterone system (RAAS)." (PMID 37299603, 2023). "Angiotensin II is a central effector molecule of activated Renin-Angiotensin system and elevated levels have been associated with severe COVID-19." (PMID 38057707, 2023). "It is predictable that the renin–angiotensin–aldosterone and kinin–kallikrein systems are dysregulated in COVID-19 (COV) patients because SARS-CoV-2 requires ACE2 to cause an infection." (PMID 37415613, 2023). "Second, the renin-angiotensin system, which is related to the regulation of the kidney, heart, and vascular physiology, is downregulated due to COVID-19, which can cause abnormalities in the function of organs such as the heart and brain." (PMID 37576978, 2023). "Several studies have reported the link between poor blood pressure control and the risk of developing severe COVID-19 due to activated renin-angiotensin-aldosterone system as well as resulting in a procoagulant and inflammatory response." (PMID 36061633, 2022). "COVID-19 begins as a respiratory infection; nonetheless, it quickly spreads to the cardiovascular system due to an imbalance in the renin-angiotensin-aldosterone pathway caused by angiotensin-converting enzyme 2 depletion." (PMID 35251711, 2022). "COVID-19 and the renin-angiotensin system (RAS) are linked by angiotensin-converting enzyme 2 (ACE2), a key enzyme in RAS that has been validated as a SARS-CoV-2 receptor." (PMID 35305693, 2022). "Rationale: Coronavirus disease 2019 (COVID-19) can cause disruption of the renin-angiotensin system in the lungs, possibly contributing to pulmonary capillary leakage." (PMID 33681257, 2021). "Among the multiple uncertainties surrounding the novel coronavirus disease (COVID-19) pandemic, a research letter published in The Lancet implicated drugs that antagonize the renin-angiotensin-aldosterone system (RAAS) in an unfavorable prognosis of COVID-19." (PMID 33852652, 2021). "Regulation of the renin-angiotensin-bradykinin system is of particular relevance in mitigating the progression of severe COVID-19, where over-activation of RAS is associated with a poor prognosis." (PMID 34862422, 2021).